CCT8 (chaperonin containing TCP1 subunit 8)
Diseases named in the same sentence as CCT8 in open-access papers (continued):
Sharing a sentence is not in itself a finding about the gene and the disease.
tumor (16 papers, 2020 to 2025). "In HCC patients, CCT8 expression was directly related to histologic grade and tumor size, and high expression was associated with poor clinical prognosis." (PMID 34676169, 2021). "For instance, the CCT8 was found to be significantly increased in gliomas and positively correlated with tumor grade and reduced survival." (PMID 41002413, 2025). "CCT8 is involved in cytoskeletal integrity and tumor invasion, with its depletion inhibiting HCC proliferation." (PMID 41312091, 2025). "In this study, MK2206, an inhibitor of AKT, inhibited CCT8-induced cell migration and tumor metastasis, suggesting that CCT8 promotes cell migration and tumor metastasis by activating AKT." (PMID 37928427, 2023). "To investigate the expression level of CCT8 in tumor tissue compared with normal tissue, we analyzed publicly available datasets." (PMID 37928427, 2023). "To investigate which process was affected by CCT8, we examined the expression of several genes which is important for tumor metastasis." (PMID 37928427, 2023). "Third, we used tissue microarray to verify the association of CCT8 and overall survival in LUAD; therefore, selection bias was inevitable during the selection of tumor areas for tissue microarray construction." (PMID 37928427, 2023). "Quantification analysis showed that CCT8 expression was significantly augmented in 71 LUAD tumor tissues compared with adjacent tissue (p < 0.0001)." (PMID 37928427, 2023). "The results showed that CCT8 expression (p = 0.033), tumor size (p < 0.001), T stage (p = 0.021), N stage (p = 0.004), and TNM stage (p = 0.006) were significantly associated with poor OS." (PMID 37928427, 2023). "As expected, CCT8 obviously increased in the tumor tissue of LUAD compared with its corresponding adjacent tissue." (PMID 37928427, 2023). "To explore the role of CCT8 in tumor metastasis, we constructed stable PC9 cells expressing CCT8 and examined the effect of CCT8 on cell mobility." (PMID 37928427, 2023). "Subsequently, ectopic expression of CCT8 facilitated cell migration and tumor metastasis, and vice versa." (PMID 37928427, 2023). "CCT8 is abnormally up-regulated in many kinds of tumors, which is related to the poor prognosis of tumor patients." (PMID 34862361, 2021). "(AUC = 0.838, 95% confidence interval = 0.773–0.876) Furthermore, higher serum CCT8 and CFL1 concentrations were significantly associated with the presence of vascular invasion, advanced tumor stage, poor disease-free survival, and poor overall survival." (PMID 34359304, 2021). "In fact, high expression of gelsolin, CapG, Stathmin, CCT8 and Rho GTPases have all been described to promote tumor cell migration, invasion and formation of metastases in various tumor entities." (PMID 32545200, 2020). "In CRC, LASP1 is reported to enhance tumor progression and metastatic potential through the activation of the mitogen‐activated protein kinase signaling pathway, Hippo signaling pathway, or through interaction with the CCT8." (PMID 40635521, 2025). "Beyond its involvement in tumor progression, CCT8 is essential for normal T cell biology." (PMID 39717265, 2024). "Given that high CCT8 expression in LUAD patients is associated with poor outcomes, we wanted to determine whether CCT8 promotes tumor metastasis." (PMID 37928427, 2023). "Ectopic expression of CCT8 facilitated cell migration and tumor metastasis, and vice versa." (PMID 37928427, 2023). "Third, we proved that CCT8 promoted cell migration and tumor metastasis in vitro and in vivo." (PMID 37928427, 2023). "Given that CHD1, CDH2, MMP2 and MMP9 play an important role in the process of EMT, we hypothesize that CCT8 mediate tumor metastasis through EMT." (PMID 37928427, 2023). "CCT8 was observed exclusively in the cytoplasm of tumor cells." (PMID 37928427, 2023). "Inhibition of AKT suppressed CCT8-induced cell migration and tumor metastasis." (PMID 37928427, 2023).
tumor (continued). "In summary, our results indicated that subunits of TRiC displayed varying degrees of abnormal expressions, and CCT2, CCT3, CCT5, CCT6A, CCT7, and CCT8 were significantly upregulated in BCa patients and their upregulation was positively correlated with BCa tumor stage." (PMID 33815471, 2021). "Data from the UALCAN database indicated that CCT4, CCT5, CCT6A, and CCT8 exhibited significantly higher promoter methylation in normal tissues than in tumor tissues, suggesting that low promoter methylation may be responsible for upregulating these CCTs in LUAD." (PMID 39259093, 2024). "All CCTs, except CCT8, exhibited significantly higher expression levels in LUAD patients with tumor stage IV as compared with stage I." (PMID 39259093, 2024). "However, the detailed mechanism of CCT8 -induced tumor metastasis is unknown." (PMID 37928427, 2023). "Conversely, CCT8 siRNA-mediated knockdown in GBM cell lines arrested the cell cycle at the G1/S checkpoint, reduced cell proliferation, and suppressed the migration and invasion abilities of tumor cells following cytoskeleton dysregulation." (PMID 41002413, 2025). "In summary, CCT4 appears to promote tumor cell proliferation by regulating cell cycle checkpoints and structural components of mitosis, echoing the cell-cycle facilitating roles observed for other CCT subunits (e.g. CCT8 in HCC)." (PMID 41403933, 2025). "According to GSE32863 sequencing data, increased expression of CCT3, CCT4, CCT5, CCT6A, CCT7, and CCT8 was observed in LUAD tumor tissues compared with paired normal tissues." (PMID 39259093, 2024). "CCT8 interacted and activated AKT to facilitate cell migration and tumor metastasis." (PMID 37928427, 2023). "What's more, we identified that CCT8 could interact and activate AKT to promote cell migration and tumor metastasis." (PMID 37928427, 2023).
cancer (14 papers, 2018 to 2025). A tumor composed of atypical neoplastic, often pleomorphic cells that invade other tissues. "CCT8 is overexpressed in many cancers, however, studies on CCT8 are limited and its role on CRC development and progression remains elusive." (PMID 34862361, 2021). "The detailed mechanism by which CCT8 promotes cancer progression remains to be elucidated." (PMID 37928427, 2023). "Hierarchical clustering of subunit expression across solid cancers highlighted CCT8 as highly consistently upregulated across all cancers (mean change = 0.76, t test), and as overall second most highly upregulated subunit besides CCT6A (mean change = 0.786, t test)." (PMID 29293508, 2018). "After examining the pulled‐down proteins by lncRNA ARHGAP5‐AS1 using mass spectrometry proteomics, we identified multiple cancer‐related proteins including CSDE1, ZC3HAV1, CCT8, CKAP4, PARP1, PEG10 and APEX1 in HepG2." (PMID 36354136, 2022). "Together with our results, we postulate that enhancing the folding of CCT8 may potentially stabilize and therefore boost the functionality of other CCT subunits, which provides a novel avenue for cancer therapy." (PMID 41203126, 2025). "However, many other previous studies have already reported the oncogenic potential of CCT8 and CFL1 in various types of cancers." (PMID 34359304, 2021). "Some of the genes were reported as cancer-related genes, such as CCT2, CCT3, CCT4, CCT6A, CCT7, CCT8." (PMID 33897772, 2021). "Intrigued by the finding that CCT8 is the most highly elevated subunit in stem cells and likely acting as assembly factor, we assessed differential expression of individual TRiC/CCT subunits across cancers." (PMID 29293508, 2018).
CCT8 also shares sentences with these, for which no sentence is quoted: lymph node metastasis (2 papers); viral infection (2); diabetic nephropathy (1); Down syndrome (1); head and neck cancer (1); Intellectual disability (1); non-Hodgkin lymphoma (1); uterine sarcoma (1).